INS (insulin)
Diseases named in the same sentence as INS in open-access papers (continued):
Sharing a sentence is not in itself a finding about the gene and the disease.
Hyperglycemia (continued). "Moreover, when subjected to hyperglycemia, the flow‐based co‐culture more than doubles the IL‐6 and insulin secretions compared to their monoculture levels and continued to rise under days of extended exposures." (PMID 40746010, 2025). "The reduction in hyperglycemia observed in HFD-fed rats treated with exosomes could be due to increased insulin sensitivity, potentially through the modulation of AKT phosphorylation levels and enhanced glucose uptake in AML12 cells." (PMID 41256259, 2025). "One study that analyzed male mice showed that the absence of ARs in pancreatic β cells leads to reduced insulin secretion in response to glucose, causing hyperglycemia." (PMID 40739991, 2025). "Similarly, MitoQ enhanced insulin secretion in pancreatic β cells exposed to hyperglycemic conditions, mimicking human hyperglycemia." (PMID 41128021, 2025). "The results of the blood tests we performed were as follows: the presence of fasting hyperglycemia was confirmed; fasting insulin resistance and normal glycemic and insulin responses to glucose load were found; and androgen, prolactin and cortisol levels were normal." (PMID 40710038, 2025). "If administered, close monitoring is necessary, as insulin and incretin suppression may induce hyperglycemia." (PMID 41267803, 2025). "Hyperglycemia usually resolves with cessation of salbutamol, but insulin administration may be necessary for severely elevated glucose levels." (PMID 41287681, 2025). "Notably, hyperglycemia enhances the production of ROS, particularly in mitochondria, thereby contributing to cellular damage in insulin‐producing tissues." (PMID 40899490, 2025). "The severe hyperglycemia observed in the homozygous KCNK16 Leu114Pro neonates could be attributed to impaired glucose-stimulated insulin secretion, which can be mitigated by insulin therapy." (PMID 40650956, 2025). "In fact, few adjustments to insulin dosing are made when dietary fat and protein are taken into consideration, a practice that leaves the child/adolescent exposed to late hyperglycemia, and therefore leads to suboptimal glycemic control and glycemic variability." (PMID 41462804, 2025). "Clinically, glycemic variability, hypoglycemia followed by rebound hyperglycemia, induced by exogenous insulin or insulin secretagogues may amplify the tumor-promoting potential of these pathways, in a tumor type–dependent manner." (PMID 41585801, 2025). "The primary mechanism involves mitigating diabetic inflammation by inhibiting hyperglycemia-induced damage pathways and restoring insulin sensitivity, which leads to lower levels of inflammatory markers in the serum, visceral and perivascular tissues, as well as within the atherosclerotic plaques." (PMID 41302207, 2025). "Gestational diabetes mellitus (GDM) is a pregnancy-related metabolic disorder characterized by hyperglycemia, which can compromise the structural integrity and contractile function of pelvic and abdominal muscles through mechanisms involving insulin resistance and altered glucose metabolism." (PMID 41295285, 2025). "Interestingly, comparable insulin sensitivity between women with isolated post-load hyperglycemia and women with normoglycaemia has been reported." (PMID 40569563, 2025). "This positions dorzagliatin as an attractive candidate for the management of PI3K inhibitor-induced hyperglycemia, with the potential to sustain the therapeutic efficacy of PI3Ki without the drawbacks associated with insulin feedback." (PMID 40573322, 2025). "As a result, patients become prone to postprandial temporary hyperglycemia that promotes continuous insulin production by the pancreatic beta-cells which ceases only when unbound active insulin rises to the level when endogenous antibodies binding capacity is exceeded." (PMID 39968421, 2025). "Maternal hyperglycemia led to an increase in insulin-positive area in fetal pancreatic islets." (PMID 40563978, 2025).
Hyperglycemia (continued). "Moreover, the excessive use of insulin due to hyperglycemia can also result in poorer clinical outcomes." (PMID 40416376, 2025). "Additionally, targeting DNMT1 potentially counteracts the pharmacological toxicity of hyperglycemia and insulin feedback stemming from PI3K inhibition." (PMID 38755637, 2024). "Therefore, any interruption in insulin delivery can lead to the rapid development of hyperglycemia, ketosis, and ensuing acidosis." (PMID 40302971, 2024). "Indeed, glucose use in insulin-dependent tissues such as muscle remains normal, as hyperglycaemia compensates for any defect in peripheral insulin action." (PMID 38334817, 2024). "Furthermore, Excessive TG accumulation in the liver, termed hepatic steatosis, further exacerbates IR by inhibiting the insulin-mediated suppression of hepatic glucose production, thereby perpetuating hyperglycemia and metabolic dysfunction." (PMID 39685081, 2024). "Type 1 diabetes (T1D) is a metabolic disorder caused by a complete lack of insulin, primarily manifested by hyperglycemia." (PMID 39776900, 2024). "Following the administration of EPE to HFD-fed mice, hyperglycemia and hyperinsulinemia were effectively controlled by dramatically decreasing blood glucose levels and insulin concentrations; furthermore, blood glycosylated HbA1c concentrations, a long-term control marker, were reduced." (PMID 39329975, 2024). "However, due to persistent hyperglycemia, dietary therapy was intensified, resulting in a reduction of insulin requirements to 4 units/day of insulin detemir and 87 units/day of insulin aspart by 38 weeks of gestation." (PMID 39744260, 2024). "Additionally, in a sheep model, F2 ewes from over-fed dams have greater instance of hyperglycemia and insulin concentrations compared with F2 ewes from control-fed dams and rams from over- or control-fed dams." (PMID 38665215, 2024). "Hyperglycemia induces the release of insulin, activating mitochondrial respiration." (PMID 38255314, 2024). "The inhibition of the PI3K/AKT signaling pathway could interrupt insulin-mediated glucose uptake and may also lead to systemic hyperglycemia due to the resulting dysregulation in glucose metabolism in multiple tissues including the liver, muscle, and fat." (PMID 39410536, 2024). "Two-thirds (68.6%, n = 35) of infants had high blood pressure during BTM treatment, but none required anti-hypertensive treatment; 15.7% (n = 8) of infants experienced hyperglycaemia, requiring the initiation or increase of insulin treatment during oral BTM treatment." (PMID 39604779, 2024). "Given that subcutaneous insulin administration bypasses the hepatic filter, which physiologically halves its concentration, the adequate dosage of boluses at meals often can be addressed with a diet that limits postprandial hyperglycemia." (PMID 39519472, 2024). "It is a noninfectious chronic disease primarily caused by reduced insulin production or tissue sensitivity to insulin that leads to hyperglycemia which is detrimental to body tissues and organs." (PMID 39759947, 2024). "There is insufficient data whether insulin treatment has an effect on patient-specific outcomes (i.e. mortality, and other adverse events) in GC-induced hyperglycemia." (PMID 38281042, 2024). "As plasma insulin does not pass through the blood-testis barrier, controlling hyperglycemia in patients have been linked to improving testicular oxidative damage." (PMID 38885232, 2024). "We hypothesized that s-osteoglycin levels increase during hyperglycemia to enhance the effect of insulin." (PMID 38549032, 2024). "Although Gpr84‐deficient mice were lean and had increased endogenous MCFAs under high‐fat diet feeding conditions, they exhibited hyperglycemia and hyperlipidemia along with lower plasma insulin and glucagon‐like peptide‐1 (GLP‐1) levels compared with wild‐type mice." (PMID 39512839, 2024).
Hyperglycemia (continued). "This program encompassed instructions on insulin administration, self-monitoring of blood glucose levels, management strategies for hypoglycemia and hyperglycemia, dietary modifications tailored to individual patient needs, and recommendations for physical exercise." (PMID 38541320, 2024). "Interestingly, chronic hyperglycemia also results in over-SUMOylation of Glis3 for decreased insulin transcription." (PMID 38540730, 2024). "In some patients with CD and acromegaly, the resulting imbalance between insulin and glucagon may lead to pasireotide-induced hyperglycemia." (PMID 39735646, 2024). "Conversely, those who are insulin-resistant exhibit impaired insulin action and glucose metabolism, resulting in increased fasting glucose levels, hyperglycemia, increased glucose uptake by muscles, increased hepatic glucose production, and increased adipose tissue lipolysis." (PMID 39731011, 2024). "T2DM occurs when there is insufficient insulin production by the pancreas, or when the insulin produced can no longer be used effectively, causing hyperglycemia." (PMID 39364789, 2024). "Although two patients with ICI-DM were insulin-free after infliximab therapy, it was difficult to determine the cause of the hyperglycemia, as neither had overt insulin deficiency, such as insufficient C-peptide or obvious DKA." (PMID 39450164, 2024). "Foetal endogenous insulin secretion is influenced by maternal hyperglycaemia." (PMID 38933924, 2024). "If patients are overweight and exhibit inadequate compliance, the administered insulin dosage may be insufficient, thereby increasing the likelihood of hyperglycemia." (PMID 39398332, 2024). "These agonists contribute to increased insulin secretion in response to hyperglycemia, suppression of glucagon secretion under hyper- or euglycemic conditions, delayed gastric emptying to prevent substantial post-meal glycemic spikes, and a decrease in calorie intake and body weight." (PMID 39560873, 2024). "Insulin pumps, which provide a continuous basal insulin rate and deliver bolus doses as required (e.g., before meals or to correct hyperglycemia), simulate physiological basal and personalized insulin secretion, showing improved glycemic outcomes compared to multiple daily injection therapy." (PMID 38397323, 2024). "The presence of insulin antibodies maybe found in patients receiving insulin but they rarely produce hypoglycaemia or hyperglycaemia as the antibodies seen in this condition have low binding capacity but high affinity to insulin." (PMID 38428138, 2024). "Thus, alterations in rhythmicity include hyperglycemia in a resting stage and increased insulin sensitivity in the activity phase in males and females." (PMID 38536791, 2024). "Women diagnosed with gestational diabetes exhibited impaired insulin secretion in response to hyperglycemia, which may indicate pancreatic beta-cell dysfunction, as well as impaired suppression of hepatic glucose production in response to insulin action." (PMID 39683486, 2024). "However, their bodies are unable to effectively utilize the insulin, leading to the coexistence of hyperglycemia and hyperinsulinemia within a single individual." (PMID 39950097, 2024). "Potential therapeutic strategies could include glycerol kinase inhibitors to mitigate hyperglycemia in an insulin‐independent manner." (PMID 39512433, 2024). "As a predictor of time to reversal of hyperglycemia in full-mass human islet transplants in chemically induced diabetic immune-compromised mouse models, the Delta insulin had superior sensitivity and specificity relative to both the index and total insulin output." (PMID 38485229, 2024). "Indeed, peripheral insulin levels are ~2-fold higher in patients with T1D compared to patients matched for hyperglycemia." (PMID 39906033, 2024).
Hyperglycemia (continued). "Importantly, endothelial cells exposed to hyperglycemia and insulin resistance can rapidly switch from aerobic glycolysis as the predominant source of energy towards enhanced fatty acid β-oxidation." (PMID 39080630, 2024). "An increasing number of animal and human studies have demonstrated that several essential elements, including zinc (Zn), iron (Fe), manganese (Mg), copper (Cu), and calcium (Ca), can affect glucose metabolism and insulin sensitivity with downstream effects on hyperglycemia and hence GDM." (PMID 39596259, 2024). "In the skeletal muscles, IR-induced insulin signaling impairment decreases glucose uptake, oxidation, and glycogen synthesis, thus elevating fasting and/or postprandial blood glucose levels, known as hyperglycemia." (PMID 39765954, 2024). "However, in the current research, EtOH-WCg was shown to ameliorate postprandial hyperglycemia by exerting the opposite effect in healthy rats, that is, by reducing insulin secretion and partially restoring the GSIS response in hyperglycemic rats." (PMID 39478960, 2024). "In patients with T2DM, SGLT2 inhibitors can increase glucose elimination by inhibiting the expression of SGLT2 protein and decreasing the reabsorption of glucose by the kidney, thus reducing hyperglycemia and improving the insulin secretion and peripheral insulin sensitivity." (PMID 38971765, 2024). "Both the mode of insulin application as well as the tightness of control for in-hospital hyperglycemia have changed considerably since the early 2000s; from sliding-scale insulin only, to tight glucose control at near-normoglycemic levels, and back to a more moderate glucose control." (PMID 38281042, 2024). "However, insulin treatment is frequently delayed and started only in cases of severe hyperglycaemia, and, when initiated, only a fraction of people achieve good glycaemic control." (PMID 38679644, 2024). "If hyperglycemia develops, an insulin infusion should be initiated according to local protocols." (PMID 39473663, 2024). "The widely accepted hypothesis is the double-phase mechanism, which proposes that the autoantibodies bind to insulin or its receptor, preventing their interaction and producing hyperglycemia." (PMID 39188435, 2024). "Authors of this paper suggested that it can provide hyperglycaemia prediction and therapy planning, classify and analyse ketonuria, diet transgressions, and blood glucose values, and make recommendations regarding diet or insulin treatment." (PMID 37022834, 2024). "However, other reports have suggested that the HIF activation can reduce tissue inflammation and improve glucose tolerance and insulin sensitivity, requiring further investigation to fully elucidate the hyperglycaemia-HIF axis." (PMID 39408212, 2024). "Moreover, hyperglycemia weakens the protective effect of insulin against MI/R injury through hyperglycemia-induced O-GlcNAcylation and inactivation of insulin signaling proteins in mice or dogs." (PMID 38790676, 2024). "This hyperglycemia triggers excessive insulin release, promoting insulin resistance over time." (PMID 39765947, 2024). "The DDQ index was associated with measures of hyperglycemia such as HbA1c and with insulin sensitivity, but not with insulin secretion." (PMID 39458507, 2024). "The diminished number of β-cells per islet coupled with decreased levels of insulin secretion per unit β-cell may explain the observed hyperglycemia." (PMID 38416754, 2024). "Furthermore, the elevated level of this substance led to hyperglycemia and decreased insulin sensitivity, typical alterations in MS." (PMID 39274918, 2024). "Skeletal muscle biopsies were obtained under basal and insulin-stimulated states during euglycemia and hyperglycemia, and these experiments showed that physiological insulin concentrations reduced the levels of markers of autophagosome formation in an mTOR-independent manner." (PMID 38971910, 2024).
Hyperglycemia (continued). "In addition, near normal glucose levels decreases tolerance for glucose fluctuations, thereby rapidly alerting the individual if insulin is needed due to hyperglycemia." (PMID 39539363, 2024). "However, PI3K is an important mediator of the action of insulin, and the use of PI3K inhibitors has been associated with hyperglycemia as an ‘on-target’ side effect." (PMID 39437820, 2024). "Based on the pathomechanism of hyperglycemia, we suggest using metformin as the first-line therapy, followed by glucagon-like peptide-1 and/or sodium-glucose co-transporter-2 inhibitor, and finally insulin in patients with pasireotide-induced hyperglycemia." (PMID 39735646, 2024). "DKA clinical manifestations occur from a lack of insulin, which causes hyperglycemia, metabolic acidosis, ketosis, and electrolyte abnormalities." (PMID 39360087, 2024). "Moreover, the authors proposed that unexplained hyperglycemia, increased insulin requirements, and the abrupt decrease in C-peptide are markers indicating the sudden loss of islet graft function, and they can contribute to the diagnosis of islet rejection." (PMID 39513890, 2024). "Because FFA2 is thought to stimulate the release GLP-1 from EECs, the absence of the receptor might lead to the opposite observation: an impaired GLP-1 response leading to hyperglycemia and diminished insulin release." (PMID 38032704, 2024). "There is some research suggesting that unexplained hyperglycemia is more common in insulin pump users using Fiasp compared with insulin aspart, which may explain the observed differences in Boost usage." (PMID 39422158, 2024). "Indeed, GBL is a sulfonylurea that abates hyperglycemia by stimulating the release of insulin from the pancreatic ß-cells." (PMID 38324798, 2024). "Notably, miR-206 emerges as a crucial mediator induced by viral infection, with its expression further heightened by hyperglycemia and concurrently repressed by insulin." (PMID 38773966, 2024). "In addition, FMT also results in microbiota-derived metabolites that are involved in managing hyperglycemia and improving insulin sensitivity." (PMID 39483608, 2024). "Artemisia vulgaris mitigated hyperglycemia and restored serum insulin." (PMID 39204151, 2024). "Anti-angiogenic TKIs used in RCC may affect glucose metabolism and insulin signaling, with both hypo- and hyperglycemia as reported side effects." (PMID 39020360, 2024). "In individuals with insulin-deficient GDM, IGFBP1 amounts were low in the first trimester but amounts during the second semester were on par with those without GDM, suggesting that other pathophysiologic factors contribute to hyperglycemia in this GDM subtype." (PMID 38627562, 2024). "Hyperglycemia, in turn, stimulates the β-cells of the pancreas to release additional insulin." (PMID 38473112, 2024). "Notably, although people can customize alarm configurations on insulin pumps and mobile apps (with the exception of fixed alerts for hyperglycemia and hypoglycemia), certain alerts still evoke feelings of annoyance, excessiveness, and other negative emotions." (PMID 38846748, 2024). "Nevertheless, the inadequate insulin secretion from pancreatic β-cells cannot counteract the hyperglycemic effects of these counter-regulatory hormones and cytokines, ultimately resulting in stress-induced hyperglycemia." (PMID 38802898, 2024). "Only two patients in the steroid group received insulin for hyperglycemia." (PMID 39586011, 2024). "However, an increase in GPx1 activity can potentially disrupt insulin function by excessively suppressing intracellular ROS required for insulin sensitization, ultimately leading to hyperglycemia." (PMID 38408934, 2024). "On the other hand, detemir insulin was useful in improving the management of a diabetic dog with concurrent Cushing’s syndrome and also prevented insulin-dependent treatment in canine patients with Cushing’s syndrome presenting with hyperglycemia." (PMID 38539988, 2024).